SIGIRR (single Ig and TIR domain containing)
Diseases named in the same sentence as SIGIRR in open-access papers (continued):
Sharing a sentence is not in itself a finding about the gene and the disease.
tumor (13 papers, 2010 to 2025). "Mechanistically, SIGIRR suppressed the sustained activation of AKT, whereas IL-37 deprived DC cells of their resistance to tumour occurrence by regulating the SIGIRR-AMPK-Akt signalling axis, which is strongly associated with CD103-positive DCs." (PMID 40583347, 2025). "In 12 samples from patients with clear cell RCC (ccRCC), the expression of the mRNA encoding the inhibitory receptor SIGIRR was consistently downregulated, which was consistent with the findings from in vitro-cultured tumour cell lines." (PMID 40583347, 2025). "We have previously shown that SIGIRR functions as a tumor suppressor in both murine models of colitis-associated tumor and in spontaneous CRC model in Apcmin mice." (PMID 35900274, 2022). "Mice deficient in the IL-1 receptor-related molecule SIGIRR show increased tumor growth, while tumor-infiltrating myeloid cells produce high levels of IL-1β and IL-6 that promote tumorigenesis." (PMID 32670290, 2020). "Furthermore, the possible dysfunction of mutated SIGIRR is linked to increased recruitment of tumor-suppressive Tregs, which are further linked with unfavorable prognosis and response to treatment." (PMID 37298214, 2023). "Hyperactivation of TLR-IL1R-mediated Akt-mTOR signaling in SIGIRR-deficient tumors leads to cell cycle progression, loss of heterozygosity of APC, and tumor initiation." (PMID 37869102, 2023). "Among them, IL-1α, IL1RAP, IL18RAP, and SIGIRR may affect the prognosis of patients by affecting local CD8+ T cell infiltration in the tumor." (PMID 39461030, 2024). "Notably, the role of SIGIRR in tumor immune regulation is to suppress inflammation and immune cell activation by negatively regulating the inflammatory signaling pathway, thereby affecting the development and progression of tumors." (PMID 39461030, 2024). "However, since SIGIRR is expressed by several cell types, including tumor-infiltrating leukocytes, it would be important to understand which cell types, in addition to cancer cells, express SIGIRR." (PMID 35814450, 2022). "Our results suggest that SIGIRR downregulation unleashes IL1 signaling intrinsic to tumor cells and that manipulating this pathway may be beneficial in ccRCC." (PMID 35814450, 2022). "In addition, an epithelial intrinsic tumor-suppressive role of SIGIRR was demonstrated in mice where SIGIRR protected from genetically driven colon carcinogenesis." (PMID 35814450, 2022). "While the inhibitory receptor SIGIRR is shut down in tumor cells, the expression of the activatory IL1R1 is maintained (data not shown), and we next asked if SIGIRR downregulation may unleash intrinsic IL1 signaling in RCC cells." (PMID 35814450, 2022). "Quite the opposite in breast cancer, SIGIRR is upregulated and promotes tumor growth." (PMID 35814450, 2022). "We herein demonstrate that SIGIRR is strikingly downregulated in RCC cells from both primary tumors and cell lines representing different tumor types." (PMID 35814450, 2022). "Lastly, GALR1 has also been documented to multiple correlations with tumour stages, lymph node status and the expression levels of SLITRK3 and SIGIRR genes." (PMID 36329447, 2022). "In a mouse model of chronic lymphocytic leukaemia (CLL), the absence of SIGIRR exacerbated the progression of leukaemia, supporting its role as a novel tumour suppressor." (PMID 40583347, 2025). "It is not known if SIGIRR downregulation is a marker of the tumor cell of origin or if it is downregulated in tumor cells during/after carcinogenesis." (PMID 35814450, 2022). "Lower levels of SIGIRR and of TOLLIP, NFRKB, TNFRSF1A, and CD14 and of two distinct MAP kinases were detected in all the cancer cell lines analyzed; on the contrary, IRAK1 and HSPD1 mRNAs were upregulated in all the tumor cells." (PMID 35814450, 2022).
tumor (continued). "To assess whether SIGIRR downregulation in RCC could be due to differential isoform expression, we performed bioinformatic analysis with Xena on the basis of RNA-seq data of transcript-specific expression for “tumor samples” and normal adjacent tissue (TCGA data)." (PMID 35814450, 2022). "However, it is not clear whether TIR8/SIGIRR exerts its activity directly onto the malignant clone or indirectly through the tumor microenvironment, and which molecular mechanisms are involved." (PMID 23112799, 2012).
cancer (10 papers, 2010 to 2023). A tumor composed of atypical neoplastic, often pleomorphic cells that invade other tissues. "Our findings highlight the role of IL-37 in harnessing antitumor immunity by inactivation of cytotoxic T cells and establish a new defined inhibitory factor IL-37/SIGIRR in cancer-immunity cycle as therapeutic targets in CRC." (PMID 35046386, 2022). "Considering that SIGIRR predominantly localizes to the ER in the cancer cells, it is possible that the SIGIRR-ATP synthase interaction occurs at the mitochondrial-ER interface." (PMID 35900274, 2022). "Along the same line, in different murine models, TIR8/SIGIRR has been demonstrated to play a key protective role in the pathogenesis of cancer-related inflammation." (PMID 23847621, 2013). "Moreover, the new defined inhibitory factor IL-37/SIGIRR in the cancer-immunity cycle is established as therapeutic targets in colorectal cancer." (PMID 35046386, 2022). "Up-regulated expressions of the hypo-methylated gDMs in cancer were observed for OAS2, MX2, APOL3, ABHD8, RASSF1, SIGIRR, and SPRED2." (PMID 36329447, 2022).
infection (9 papers, 2012 to 2020). The state of being infected such as from the introduction of a foreign agent such as serum, vaccine, antigenic substance or organism. "Consistent with the TLR inhibiting role of SIGIRR, SIGIRR deficient mice showed exaggerated inflammation and increased lethality after infection with Mtb despite an efficient control of mycobacterial growth." (PMID 25887604, 2015). "Recently we showed that mice deficient in Single IgG IL-1 Related Receptor (SIGIRR) exhibit increased susceptibility to infection by two natural enteric bacterial pathogens of mice, namely Citrobacter rodentium and Salmonella enterica serovar Typhimurium." (PMID 25033044, 2014). "Our data suggest that SIGIRR localizes in the membrane and the cytosol and associates with MyD88 in uninfected cells, but some SIGIRR may also associate with the C. trachomatis inclusion during infection, according to our immunoprecipitation results." (PMID 32210474, 2020). "For example, in mice with SIGIRR deficiency infected with Streptococcus pneumoniae, there was delayed mortality, reduction in the dissemination of the infection and reduced bacterial load in the lungs despite increased interstitial and perivascular inflammation in comparison to controls." (PMID 32210474, 2020). "In the current study, we tested the role of MyD88, as well as individual receptors and as expected, loss of MyD88 left Sigirr −/− mice suffering severe mucosal damage and rapidly succumbing to infection, much like Myd88 −/− mice that express SIGIRR." (PMID 23950714, 2013).
Bacterial infection (1 paper, 2012). "Bacterial infection of intestinal epithelial cells and exposure to flagellin transiently decreased TIR8/SIGIRR protein expression." (PMID 23112799, 2012).
intestinal diseases (1 paper, 2025). "In conclusion, SIGIRR may be involved in regulating the defence mechanism of the intestinal epithelium, and its abnormal expression regulation is closely associated with the occurrence and development of intestinal diseases." (PMID 40583347, 2025). "Uncontrolled transcription of the SIGIRR gene may lead to the abnormal proliferation of IECs, resulting in excessive inflammation and antimicrobial responses that ultimately contribute to the development of intestinal diseases." (PMID 40583347, 2025).
SIGIRR also shares sentences with these, for which no sentence is quoted: aspergillosis (3 papers); candidiasis (3); necrotizing enterocolitis (3); hepatocellular carcinoma (2); intestinal cancer (2); urinary tract infection (2); adenocarcinoma (1); adenoma (1); allergic rhinitis (1); Alzheimer disease (1); and Muscular Disorder (1); asthma (1); atherosclerosis (1); benign prostatic hyperplasia (1); bladder cancer (1); Clear Cell Renal Cell Carcinoma (1); cognitive decline (1); cognitive defects (1); cystic fibrosis (1); endotoxemia (1); experimental autoimmune encephalomyelitis (1); glomerulonephritis (1); head-and-neck tumors (1); Hepatitis (1); infectious colitis (1); infectious disease (1); infestations (1); Kawasaki disease (1); major depressive disorder (1); metastatic cancer (1).
A further 9 diseases each share a sentence with SIGIRR in 1 paper.